PCSK9 (proprotein convertase subtilisin/kexin type 9)
Diseases named in the same sentence as PCSK9 in open-access papers (continued):
Sharing a sentence is not in itself a finding about the gene and the disease.
melanoma (continued). "Notably, while PCSK9 expression is significantly upregulated in melanoma and bladder tumors, it is downregulated in renal clear cell carcinoma, yet relatively higher expression among renal tumors still predicts poorer survival." (PMID 40576911, 2025). "PCSK9 produced by tumors plays a pivotal role in the development of melanoma by exerting systemic effects on the immune system, facilitating immune evasion by the melanoma cells." (PMID 40362754, 2025). "In preclinical study, in neuroglioma and NSCLC knockdown of PCSK9 gene determinants cancer apoptosis using the caspase‐3 and XIAP/p‐Akt pathways and in melanoma-bearing mice PCSK9 gene silencing considerably boosts the response to immune checkpoint inhibitors (ICIs)." (PMID 38509261, 2024). "Moreover, PCSK9 expression appears to have a profound impact on the systemic immune system, aiding in the immune evasion of melanoma cells." (PMID 38974243, 2024). "The findings indicate that HMGCR inhibitors(statins) might contribute to melanoma development, whereas PCSK9 inhibitors (iromazumab and aliciumab) could offer protective effects against melanoma." (PMID 38974243, 2024). "Additionally, Ahnak’s role in regulating melanoma metastasis to lung epithelial cells via PCSK9 expression has been identified, where PCSK9 acts as an inhibitor of TNF α-mediated apoptosis, thus promoting melanoma cell metastasis to the lungs." (PMID 38974243, 2024). "While PCSK9 has been elegantly demonstrated to facilitate immune evasion by downregulation of MHC I from the cancer cell surface, our research reveals a systemic influence of PCSK9 on the immune system that is likely beyond its impact on MHC I at least in melanoma." (PMID 36588164, 2023). "Nonetheless, host PCSK9 is likely involved in melanoma growth." (PMID 36588164, 2023). "This suggests a scenario for which host PCSK9 further facilitates melanoma progression; in its absence, a larger sample size may be required to detect statistically meaningful elevations of immune checkpoint expression in melanoma." (PMID 36588164, 2023). "The role of PCSK9 in enhancing hepatocellular tumors and melanoma metastasis has been validated." (PMID 37103355, 2023). "The dominant aspect of PCSK9 in promoting melanoma is its systemic impact on the immune system." (PMID 36588164, 2023). "Moreover, PCSK9 inhibition was suggested as a promising way to enhance immune checkpoint therapy for melanoma (B16F10), triple-negative mouse breast cancer (4T1), and colorectal cancer (MC38 and CT26)." (PMID 37103355, 2023). "Moreover, PCSK9 gene silencing reduces liver metastasis in melanoma-bearing mice through induction of intra-tumoral CD3+CD8+ lymphocytes levels." (PMID 36900189, 2023). "PCSK9 systemically affects the immune system, contributing to melanoma immune evasion." (PMID 36588164, 2023). "We have thus taken a comprehensive approach to investigate PCSK9’s role in melanoma." (PMID 36588164, 2023). "Tumor-derived PCSK9 plays a critical role in melanoma pathogenesis." (PMID 36588164, 2023). "In comparisons to tumors produced in C57BL/6 mice, PCSK9 and D374Y allografts generated in Pcsk9−/− mice accumulated less esterified cholesterol (ORO staining) but not active cholesterol (filipin staining), implying a role of tumor-derived PCSK9 in facilitating cholesterol availability to melanoma." (PMID 36588164, 2023). "Another serine protease, proprotein convertase subtilisin/kexin type 9 (PCSK9), has been shown to be raised in obese human serum and also linked to melanoma metastasis in mice through its role in maintaining high circulating cholesterol levels, and likely activation of the TNFα pathway." (PMID 36038791, 2022).
melanoma (continued). "The observation presented here that LRP-1 protein levels could also be regulated by PCSK9 is significant, since PCSK9 was recently shown to modulate the metastatic potential of melanoma cells and LRP-1 is a well-known factor involved in tumour metastasis." (PMID 23675525, 2013). "A notable role of PCSK9 is the modulation of MHC (major histocompatibility complex) I expression on cancer cell surfaces, aiding melanoma cells in evading immune detection." (PMID 38760735, 2024). "Consequently, targeting PCSK9 could be promising for the preventive treatment of melanoma." (PMID 38760735, 2024). "Despite the long-term use of PCSK9 inhibitors for managing LDL-C levels, their relationship with melanoma has been sparsely researched." (PMID 38974243, 2024). "PCSK9 was negatively correlated with the expression of most MHC-II subtypes in STAD (P < 0.05) and with several MHC-II subtypes in melanoma." (PMID 38600469, 2024). "Thus, the risk reduction through PCSK9 inhibitors for treating melanoma might not align with the magnitudes estimated in this MR study." (PMID 38974243, 2024). "In both syngeneic mouse models for colon cancer and melanoma, anti-PD1 therapy displayed synergy with anti-PCSK9 antibody in inhibition of tumor growth." (PMID 36588164, 2023). "The common DEGs shared by PCSK9 and D374Y tumors stratify poor OS of skin cutaneous melanoma (SKCM) and worse outcome in melanoma as well as other cancers treated with ICB." (PMID 36588164, 2023). "Therefore, PCSK9 is capable of mediating the degradation of LRP-1 in both human HEK293 and HepG2 cells, as well as in mouse B16 melanoma cells." (PMID 23675525, 2013). "This possibility is consistent with Q152H inhibiting melanoma growth compared to EV, particularly in Pcsk9−/− mice, which might be attributable to the LOF mutant’s ability to suppress endogenous wild-type PCSK9." (PMID 36588164, 2023). "In support of the positive relationship between DNA methylation and PCSK9 dysregulation, our study discovered that melanoma, non-small cell lung cancer, cervical squamous cell carcinoma, ESCA, LIHC, SARC, BLCA, and BRCA all had greater levels of PCSK9 methylation." (PMID 37860186, 2023). "This led us to identify the low density lipoprotein receptor-related protein 1 (LRP-1) as a receptor whose degradation is induced by PCSK9 in two melanoma cell lines, in which we previously showed that the lack of host mouse PCSK9 reduced their metastasis in liver." (PMID 23675525, 2013). "Interestingly, our bioinformatics analysis has verified the negative relations of PCSK9 on MHC-II expression, especially in the gastric cancer and melanoma cohorts." (PMID 38600469, 2024). "In addition, in cases of the liver metastasis of melanoma cells (B16F1), mice lacking the PCSK9 gene showed lower levels of metastasis when on a chow diet." (PMID 36552895, 2022).
dyslipidaemia (28 papers, 2016 to 2025). "The P value of the association between PCSK9 and dyslipidaemia markedly improved from P = 4.02 × 10−17 (odds ratio (OR) = 0.35; 95% CI, 0.27 to 0.46) to P = 7.69 × 10−112 (OR = 0.63; 95% CI, 0.60 to 0.65) in the ptvolink2pcnt model." (PMID 37794183, 2023). "This is the first demonstration that pSS patients, despite lower prevalence of dyslipidaemia and higher CV risk profile, are characterized by a 3-fold increase in PCSK9 levels in comparison to HCs." (PMID 37759784, 2023). "Briefly, APOE and LPA are components of LDL-C while ANGPTL3 and PCSK9 are known drug targets for dyslipidaemia treatment." (PMID 40689090, 2025). "Our study highlighted potential causal links between plasma proteins, dyslipidaemia, and CVDs in South Asians and highlighted protein targets, including CELSR2, PCSK9, ANGPTL3, and Apolipoprotein(a) (LPA)." (PMID 40689090, 2025). "Administration of PCSK9 inhibitors appears to be an effective and safe option for the treatment of dyslipidaemia in patients with IMNM." (PMID 40249406, 2025). "In second place in the treatment of dyslipidaemia are currently the PCSK9 inhibitors—alirocumab, evolocumab, and inclisiran, which is not strictly a PCSK9 inhibitor, but is often included in the same group of drugs." (PMID 38988669, 2024). "The aim of this review was to present the results of several meta-analyses conducted in the field of dyslipidaemia over the last 5 years, with a focus on PCSK9 inhibition." (PMID 38988669, 2024). "Proprotein convertase subtilisin/kexin type 9 (PCSK9) inhibitors have been approved to treat dyslipidaemia." (PMID 37937036, 2023). "The cholesterol lowering drugs statins and PCSK9 inhibitors reduce levels of circulating ceramides and other sphingolipids in patients with dyslipidaemia." (PMID 35331214, 2022). "The first approved monoclonal antibodies for the treatment of dyslipidaemia, PCSK9 inhibitors, are currently used as second-line treatment for patients with unregulated lipid levels on statin or statin combination therapy." (PMID 35890138, 2022). "Monoclonal antibodies that inhibit proprotein convertase subtilisin-kexin type 9 (PCSK9) reduce low-density lipoprotein (LDL) cholesterol levels and subsequently the risk of cardiovascular events in patients with dyslipidaemia." (PMID 30650126, 2019). "It is not clear what proportion of patients this would apply to, but it was estimated in the US in 2019 that PCSK9 inhibitors were used in <1% of patients with either dyslipidaemia (including familial hypercholesterolaemia), elevated LDL-C (≥130 mg/dL [3.4 mmol/L]), or pre-existing CHD." (PMID 38325890, 2024). "Currently, there are multiple pharmacologic options that can be used in the management of dyslipidaemia, such as statins, ezetimibe, bempedoic acid, PCSK9 inhibitors, n-3 polyunsaturated fatty acids or fibrates, to name only a few, while many other are under development." (PMID 38399434, 2024). "Preprotein converting enzyme subtilisin/Kexin 9 (PCSK9) inhibitors are novel pleiotropy lipid-lowering drug with dual anti-inflammation and lipid-lowering effects, and represent a new clinical pathway for rapid correction of dyslipidaemia." (PMID 37723117, 2023). "Although PCSK9 inhibitors are widely known within the clinicians ́ community, further education seems to be needed regarding the enormous benefits for patients at very high risk of ASCVD with dyslipidaemia." (PMID 37216363, 2023). "In 2007, PCSK9 emerged as a novel target to treat dyslipidaemia." (PMID 34356856, 2021). "Could rapid attenuation of dyslipidaemia by PCSK9 inhibitorsattenuate endothelial erosion on complex plaques, indirectly diminishing thromboticcomplications?" (PMID 26726043, 2016).
dyslipidaemia (continued). "The blunted reduction of LDL levels compare to the reported trials might be explained by the concomitant therapy with steroids and other immunosuppressive medications, which themselves have been shown to lead to dyslipidaemia after transplantation and may counteract the PCSK9 inhibition." (PMID 30650126, 2019). "Furthermore, it may be hypothesised that increased hepatic PCSK9 expression is involved in the initiation of mixed dyslipidaemia." (PMID 28545518, 2017). "Our study confirmed key proteins (PCSK9, ANGPTL3, LPA), identified potential novel targets (GSTA1, GSTA3, EPPK1, PECR, and PLA2G15), and strengthened evidence for CELSR2 and GAS6 in dyslipidaemia." (PMID 40689090, 2025). "These associations included ACVRL1 and ENG with hereditary haemorrhagic telangiectasia, GRN with dementia, NOTCH1 with chronic lymphocytic leukaemia, PCSK9 and ANGPTL3 with dyslipidaemia, and others." (PMID 37794183, 2023). "A direct effect of PCSK9 on platelets independent of its effects on dyslipidaemia has been recently shown as PCSK9 inhibitors can enhance oxidative stress (as a result of the activation of the Nox2 and cPLA2 signaling cascades) and block platelet activation in Wt human platelets." (PMID 33834043, 2021).
hypertriglyceridemia (28 papers, 2013 to 2025). A laboratory test result indicating elevated triglyceride concentration in the blood. "Hypertriglyceridaemia remains a significant ASCVD risk despite low LDL-C in statin or proprotein convertase subtilisin/kexin type 9 inhibitor-treated patients." (PMID 39171323, 2024). "The rs662145 in PCSK9 is newly found to be associated with hypertriglyceridemia." (PMID 31480784, 2019). "Moreover, deficiency of intestinal PCSK9 has been found to reduce postprandial hypertriglyceridemia by increasing the clearance of TG-rich lipoproteins." (PMID 29180444, 2018). "The fourth research direction is a hot research area in recent years (green cluster) and includes hypertriglyceridemia, ApoB, LP(a), omega-3 fatty acids, icosapent ethyl, PCSK9 inhibitors, EPA, DHA." (PMID 38017531, 2023). "Research has shown that knockout of PCSK9 in mice clearly inhibited postprandial hypertriglyceridemia." (PMID 32169071, 2020). "In mice, we showed that PCSK9 overexpression is accompanied with hypertriglyceridemia due to VLDL overproduction." (PMID 23298392, 2013). "In parallel with a higher increase of PCSK9, the hypertriglyceridemia was also more robust in HFruc2 diet." (PMID 23298392, 2013). "Besides the prominent expression of PCSK9 in the liver, PCSK9 is also found in the intestine, and therefore, was considered in postprandial hypertriglyceridemia." (PMID 35162992, 2022). "However, in individuals with hypertriglyceridemia, evolocumab played a modest role in lowering TG levels, indicating that anti-PCSK9 mAbs may impact TG levels in a dose-dependent manner." (PMID 32169071, 2020). "Thus this finding may suggest that PCSK9 antibodies might also be used as TG-lowering agents in hypertriglyceridemia; however, this effect needs to be further proved in clinical trials." (PMID 31779098, 2019). "The green cluster includes triglycerides (TG), hypertriglyceridemia, LDL-C, apolipoprotein b (ApoB), lipoprotein, omega-3 fatty acids, icosapent ethyl, PCSK9 inhibitors, eicosapentaenoic acid (EPA), docosahexaenoic acid (DHA)." (PMID 38017531, 2023). "Thus, high level of serum PCSK9, promoting VLDL-R and CD36 degradation, could also contribute to elevated serum VLDL–cholesterol and FFA level leading to hypertriglyceridemia found in lipectomized rats." (PMID 30483910, 2019). "Although statins, the intestinal cholesterol transporter inhibitor (namely, ezetimibe) and PCSK9 inhibitors reduce serum levels of LDL-C, they do not act on Hypertriglyceridemia and HDL levels." (PMID 40142198, 2025).